ASRGL1 (asparaginase and isoaspartyl peptidase 1)
Description:
Has both L-asparaginase and beta-aspartyl peptidase activity. May be involved in the production of L-aspartate, which can act as an excitatory neurotransmitter in some brain regions. Is highly active with L-Asp beta-methyl ester. Besides, has catalytic activity toward beta-aspartyl dipeptides and their methyl esters, including beta-L-Asp-L-Phe, beta-L-Asp-L-Phe methyl ester (aspartame), beta-L-Asp-L-Ala, beta-L-Asp-L-Leu and beta-L-Asp-L-Lys. Does not have aspartylglucosaminidase activity and is inactive toward GlcNAc-L-Asn. Likewise, has no activity toward glutamine.
Synonyms: ALP; CRASH; FLJ22316; ALP1
Tractability: Small molecule: a structure with a bound ligand is known. PROTAC: ubiquitination databases record sites on it; its protein half-life has been measured.
Gene: Protein-coding gene on chromosome 11 (62,337,439 to 62,393,412, forward strand). Ensembl gene ENSG00000162174.
Subcellular location: Cytoplasm
Subcellular location (Human Protein Atlas): Microtubules; Cytokinetic bridge; Nucleoplasm
Pathways (Reactome):
Metabolism: Phenylalanine metabolism
Gene Ontology:
Molecular function: asparaginase activity; beta-aspartyl-peptidase activity; N4-(beta-N-acetylglucosaminyl)-L-asparaginase activity; hydrolase activity
Biological process: L-asparagine catabolic process
Cellular component: cytoplasm; nucleus; cytosol; photoreceptor inner segment
Genetic constraint (gnomAD): Loss-of-function variants: 16 observed, 21.67 expected, observed/expected ratio (o/e) 0.74, 90% interval 0.5 to 1.12. The upper end of that interval is the gene's LOEUF score, 1.12, which puts it in group 4 of 6, group 1 being the genes least tolerant of losing a copy. Missense variants: 412 observed, 419.14 expected, observed/expected ratio (o/e) 0.98, 90% interval 0.91 to 1.07. Synonymous variants: 165 observed, 159.66 expected, observed/expected ratio (o/e) 1.03, 90% interval 0.91 to 1.18.
Homologues: Orthologues: chimpanzee ASRGL1 (98% identical), macaque ASRGL1 (96% identical), pig ASRGL1 (82% identical), guinea pig ASRGL1 (80% identical), mouse Asrgl1 (78% identical), rat Asrgl1 (77% identical), rabbit ASRGL1 (73% identical), dog ASRGL1 (70% identical), tropical clawed frog asrgl1 (60% identical), zebrafish asrgl1 (60% identical), Drosophila melanogaster CG7860 (42% identical). Paralogues in human: TASP1 (38% identical), AGA (28% identical).
Diseases named in the same sentence as ASRGL1 in open-access papers:
ASRGL1 is named in the same sentence as 32 diseases in open-access papers, as found by Europe PMC text mining. Sharing a sentence is not in itself a finding about the gene and the disease. The quoted sentences say what the papers report.
endometrial cancer (6 papers, 2019 to 2025). Primary or metastatic malignant neoplasm involving the endometrium (mucous membrane that lines the endometrial cavity). "Several studies reported that loss of ASRGL1 is an independent prognostic factor in endometrial cancer." (PMID 37387559, 2023). "ASRGL1 encodes the enzyme that catalyzes the hydrolysis of l -asparagine to l-aspartic acid and ammonia and plays a protective role in endometrial carcinoma." (PMID 36829161, 2023). "Low expression of Asparaginase-Like 1 Protein (ASRGL1) has been suggested as a marker for poor prognosis in endometrial carcinoma, whereas reduced levels of Solute carrier family 27 member 2 (SLC27A2) have been associated with poor survival in lung cancer." (PMID 31337362, 2019). "Interestingly, the gene PGM2 has not been shown to be a biomarker for colorectal cancer while the gene ASRGL1 has been shown to be prognostic in the prediction of endometrial cancer." (PMID 37286944, 2023). "Interestingly, ASRGL1 has been identified as a biomarker of endometrial cancer, as well as an antigen in rodent sperm." (PMID 30893341, 2019). "Additionally, another study identified a a panel of fivegenes (ASRGL1, RHEX, SCGB2A1, SOX17, and STX18) as biomarkers for predicting lymph node metastasis in early-stage endometrial cancer patients." (PMID 39980551, 2025).
prostate carcinoma (3 papers, 2019 to 2022). A carcinoma that arises from epithelial cells of the prostate gland. "In the recent study based on the TCGA data, elevated expression of ASRGL1 gene was found to be associated with biochemical recurrence of prostate cancer." (PMID 31447885, 2019). "Furthermore, authors revealed such genes for the TMPRSS2-ERG prostate cancer molecular subtype (B4GALNT4, ASRGL1, MYBPC1, RGS11, SLC6A14, GALNT13 and ST6GALNAC1)." (PMID 36077746, 2022). "Additionally, we revealed such genes for the TMPRSS2-ERG prostate cancer molecular subtype (B4GALNT4, ASRGL1, MYBPC1, RGS11, SLC6A14, GALNT13, and ST6GALNAC1)." (PMID 31447885, 2019).
retinal degeneration (3 papers, 2017 to 2022). Degeneration of the retina. "A homozygous missense mutation G178R in the human asparaginase like-1 gene (ASRGL1) is associated with early onset retinal degeneration in a consanguineous Pakistani pedigree." (PMID 36011372, 2022). "Earlier in vitro studies revealed a significant loss of asparaginase activity due to the G178R mutation that was detected in patients with retinal degeneration and suggested that appropriate retinal structure and function are dependent on ASRGL1 activity." (PMID 36011372, 2022). "In this study, we showed that a mouse model with a homozygous null allele provides key insights into the role of ASRGL1 in retinal degeneration." (PMID 36011372, 2022). "We previously identified a homozygous G178R mutation in human ASRGL1 (hASRGL1) through whole-exome analysis responsible for early onset retinal degeneration (RD) in patients with cone–rod dystrophy." (PMID 36011372, 2022). "Despite this progress, the molecular mechanism underlying ASRGL1’s involvement in retinal degeneration is unknown." (PMID 36011372, 2022). "Ayyagari and colleagues showed that a mutant allele of asparaginase like-1 (ASRGL1) identified in a family with inherited retinal degeneration induced protein aggregation in monkey kidney fibroblast-like COS-7 cells, and retinal photoreceptor degeneration in zebrafish larvae." (PMID 28882119, 2017). "While the Asrgl1 gene ablated mouse models establish the involvement of this gene in retinal degeneration, the specific role of ASRGL1 and the mechanism underlying the progressive retinal degeneration due to the loss of ASRGL1 expression and/or activity are unknown." (PMID 36011372, 2022). "Importantly, the retinal phenotype of Asrgl1mut/mut mice is consistent with the phenotype observed in patients harboring the G178R mutation in ASRGL1 confirming a critical role of ASRGL1 in the retina and the contribution of ASRGL1 mutations in retinal degeneration." (PMID 36011372, 2022). "The onset of retinal degeneration is observed to be earlier in the Asrgl1mut/mut mouse model at 3 months compared with the late-onset degeneration reported in the Asrgl1 KO model at 8 months." (PMID 36011372, 2022). "Our results suggested an important role of glucocorticoid receptor signaling in the physiology of Asrgl1-related retinal degeneration." (PMID 35118070, 2021). "Asrgl1 ablation in mice resulted in a typical retinal degeneration phenotype with decreased electroretinogram (ERG) response; thinner outer nuclei layer (ONL), inner segment (IS), and outer segment (OS); and decreased rod and cone proteins." (PMID 35118070, 2021).
colon cancer (2 papers, 2019 to 2025). "The curves present survival data for the two groups of colon cancer patients based on gene expression level (high or low) of SPINK4, RETNLB, ASRGL1, CLCA1, and FCGBP (rows)." (PMID 31337362, 2019). "Additionally, our study found that the expression of ASRGL1 and EREG can influence the sensitivity of colon cancer to certain antitumor drugs, and the specific mechanisms underlying these effects warrant further exploration." (PMID 39883700, 2025).
hepatocellular carcinoma (2 papers, 2021 to 2025). A malignant tumor that arises from hepatocytes. "ASRGL1 strongly inhibits the development of hepatocellular carcinoma by inhibiting the formation of the cyclin B/CDK1 complex, ultimately leading to the failure of transition from the G2 to M phase of the cell cycle." (PMID 39883700, 2025). "Correlation of ASRGL1 expression and clinical prognosis in hepatocellular carcinoma with different clinicopathological factors by Kaplan-Meier plotter." (PMID 34249720, 2021). "However, the expression and biological function of ASRGL1 in hepatocellular carcinoma (HCC) are still unclear." (PMID 34249720, 2021).
infertile (2 papers, 2022 to 2023). "Finally, six proteins were found to be unique in the infertile group; these were neuroblast differentiation-associated protein (AHNAK), isoaspartyl peptidase/L-asparaginase (ASRGL1), UMP-CMP kinase (CMPK1), phosphoglucomutase-1 (PGM1), cornulin (CRNN), and suprabasin (SBSN)." (PMID 35719135, 2022). "Other genes are related to symptoms that are still under investigation, such as neurological sequels (CYB561 and LCMT2) and infertility (RPSAP58 and ASRGL1)." (PMID 36674947, 2023).
lung carcinoma (2 papers, 2019 to 2021). "In addition, high ASRGL1 expression was correlated negatively with OS of patients with lung cancer, but not with PPS." (PMID 34249720, 2021).
ovarian carcinoma (2 papers, 2016 to 2021). A malignant neoplasm originating from the surface ovarian epithelium. "Similarly, ASRGL1 (asparaginase like 1) is highly expressed in ovarian carcinoma and confers a selective growth advantage; accordingly, our data show that ASRGL1 is preferentially expressed in SKOV-3 cells where it is downregulated following PAX8 silencing." (PMID 27259239, 2016).
breast carcinoma (1 paper, 2021). "In breast cancer, the strong expression of ASRGL1 in tumors can promote proliferation and inhibit apoptosis in cancer cells." (PMID 34249720, 2021). "For example, ASRGL1 is highly expressed in breast carcinoma compared with the adjacent tissues, suggesting it can serve as a biomarker for cancer diagnosis." (PMID 34249720, 2021).
cholangiocarcinoma (1 paper, 2021). A carcinoma that arises from the intrahepatic biliary tree (intrahepatic cholangiocarcinoma) or from the junction, or adjacent to the junction, of the right and left hepatic ducts (hilar cholangiocarcinoma). "According to the TIMER 2.0 database, ASRGL1 mRNA is strongly expressed in a variety of cancers, including cholangiocarcinoma, pancreatic cancer, and HCC." (PMID 34249720, 2021).
colorectal adenocarcinoma (1 paper, 2025). The most common type of colorectal carcinoma. "There is also evidence suggesting that ASRGL1, as a pivotal gene related to Th17 cells, is highly correlated with the prognosis of colorectal adenocarcinoma." (PMID 39883700, 2025).
early-onset retinal dystrophy (1 paper, 2021). "Although the patients exhibited an early-onset retinal dystrophy, late-onset retinal dystrophy was observed in Asrgl1 KO mice." (PMID 35118070, 2021).
emphysema (1 paper, 2019). "Furthermore, RNA-seq profiling revealed some significantly associated emphysema genes, including asparaginase-like 1 (ASRGL1), latrophilin 2 (LPHN2), and endothelin receptor type B (EDNRB)." (PMID 31651369, 2019).
endometrial tumors (1 paper, 2021). "ASRGL1 is considered as a biomarker of endometrial tumors and low ASRGL1 expression is associated with a poor outcome of the cancer." (PMID 34249720, 2021).
endometrioid endometrial adenocarcinoma (1 paper, 2019). "On the contrary, decreased expression of ASRGL1 was significantly associated with poor prognosis and reduced disease-specific survival in endometrioid endometrial adenocarcinoma." (PMID 31447885, 2019).
endometrioid endometrial carcinoma (1 paper, 2021).
frontotemporal lobe dementia (1 paper, 2024). "We compared the expression of ASRGL1 and TARDBP between ALS individuals and controls (frontotemporal lobe dementia (FTLD) and non-neurological cases) in different subtypes of neurons and glia, in motor cortex (BA4) and in dorsolateral prefrontal cortex (BA9), as a control region." (PMID 38755145, 2024).
kidney tumor (1 paper, 2023). "Using IHC data from the Protein atlas database, we observed strong or moderate staining for ACAA2, ACAT1, ASRGL1, and AKR1B10, weak staining for ANGPTL4 and ABCC2 in normal kidney tissues and opposite staining results in kidney tumor samples." (PMID 36829161, 2023).
liver cancer (1 paper, 2021). An epithelial or non-epithelial malignant neoplasm that arises from the liver. "However, the specific expression pattern and function of ASRGL1 in liver are still unclear, but it has been reported that Asn can inhibit tumor proliferation, invasion, and migration in liver cancer." (PMID 34249720, 2021). "In our study, it was found that ASRGL1 was highly expressed in liver cancer, which may play a role in promoting tumor development through the antagonism of asparaginase and lead to poor prognosis of patients." (PMID 34249720, 2021).
proteinopathy (1 paper, 2024). "Loss of ASRGL1 leading to TDP-43 proteinopathy may be a critical mechanism in ALS pathophysiology." (PMID 38755145, 2024). "In conclusion, we demonstrate the importance of ASRGL1 depletion in the formation of TDP-43 proteinopathy." (PMID 38755145, 2024). "To further study the association between ASRGL1 loss in ALS individuals and the presence of cytoplasmic TDP-43, we explored whether TDP-43 could be a substrate of ASRGL1 and if the loss of this enzyme could have a role in the formation of TDP-43 proteinopathy." (PMID 38755145, 2024).
retinitis pigmentosa (1 paper, 2021). Retinitis pigmentosa (RP) is an inherited retinal dystrophy leading to progressive loss of the photoreceptors and retinal pigment epithelium and resulting in blindness usually after several decades. "Although variants in ASRGL1 have been reported in retinitis pigmentosa (RP) patients, the in vivo functions and mechanisms of ASRGL in RP remains unknown due to the lack of suitable disease models." (PMID 35118070, 2021).
tumor (6 papers, 2010 to 2025). "The analysis of the UALCAN database indicated that the expression of ASRGL1 in HCC tissues also varied in different clinical tumor stages, with a significant positive correlation between ASRGL1 expression and the degree of tumor malignancy." (PMID 34249720, 2021). "Subsequently, using UALCAN, the expression of ASRGL1 was found to be correlated significantly with race, age, sex, body weight, tumor grade, and nodal metastasis status." (PMID 34249720, 2021). "From the database analysis, we found that ASRGL1 was extensively involved in tumor immune invasion." (PMID 34249720, 2021). "All results indicated that ASRGL1 may participate widely in tumor immune cell infiltration and have a vital role in the occurrence of HCC." (PMID 34249720, 2021). "Interestingly, studies indicate the relationship of ASRGL1 expression with hormone receptor status, which builds a link between glutamine and amino acid metabolism with hormone homeostasis, as EC is hormone‐dependent tumor." (PMID 37387559, 2023). "The expression levels of PHGDH and ASRGL1 were significantly correlated with four or more clinicopathologic features (stage, grade, LNM, peritoneal cytology, tumor state, and survival status)." (PMID 37387559, 2023). "Still related to asparagine metabolism, ASRGL1 expression positively correlates with HCC tumor stages and promotes tumor development and progression by modulating immune infiltration." (PMID 37108625, 2023).
cancer (2 papers, 2016 to 2021). A tumor composed of atypical neoplastic, often pleomorphic cells that invade other tissues. "Interestingly, both AGA and ASRGL1, related to N4-(beta-N-acetylglucosaminyl)-L-asparaginase activity, are highly connected in the reconstructed network, which may provide clues as to how these two genes interact with other cancer genes." (PMID 27830726, 2016).
bacterial infection (1 paper, 2024). "Some overexpressed genes in BM samples are associated with infections, such as ASRGL1, NR2F6, and OLFML3 for bacterial infection." (PMID 38902725, 2024).
neurodegenerative disease (1 paper, 2024). A disorder of the central nervous system characterized by gradual and progressive loss of neural tissue and neurologic function. "Dysfunction or loss of ASRGL1 might be a common link between several neurodegenerative diseases, whose pathogenic aggregative proteins seem to act like prions." (PMID 38755145, 2024). "Interestingly, ASRGL1 interacts with several other proteins associated with ALS and other neurodegenerative diseases." (PMID 38755145, 2024).
ASRGL1 also shares sentences with these, for which no sentence is quoted: asthenozoospermia (2 papers); Alzheimer disease (1); colorectal cancer (1); dementia (1); multiple sclerosis (1); pancreatic cancer (1); viral infections (1).